EGFR (epidermal growth factor receptor)
Diseases named in the same sentence as EGFR in open-access papers (continued):
Sharing a sentence is not in itself a finding about the gene and the disease.
lung cancer (continued). "A genetically engineered inducible EGFR L858R transgenic mouse model, identified as a model of human lung cancer development that can be used to assess the effectiveness of drugs, was used for investigating lung cancer progression in mice with or without an HFD." (PMID 37929799, 2023). "However, no degradation of wild-type EGFR in A549 lung-cancer cells was observed." (PMID 36986673, 2023). "Importantly, lower mutation rates in two FDA‐approved therapeutic targets, namely, EGFR in lung cancer and KRAS in colorectal cancer, were identified, indicating that young patients with lung cancer or colorectal cancer may have a smaller chance of benefitting from targeted therapies." (PMID 37610374, 2023). "They played roles in mediating NSCLC cell proliferation, metastasis, and drug resistance by transactivating EGFR signaling, implying that the crosstalk between GPCR and EGFR may provide the opportunities to discover novel pharmacological approaches to treat lung cancer patients." (PMID 35013118, 2022). "Similarly, lung cancer line NCIH1975 has a high dependency on EGFR and could be sensitized while A549 could not." (PMID 34663908, 2022). "In addition, whether the disturbance and imbalance of mitochondrial Ca2+ can promote the EGFR-TKI sensitivity of lung cancer cells has not yet been studied." (PMID 36712673, 2022). "The mechanism accounting for the difference in the number of LDs in lung cancer cells is not known at this moment, but the types of driver mutations seem to play a role, as the number of LDs was comparatively higher in all tested KRAS-mutated cells than in EGFR-mutated cells." (PMID 36293388, 2022). "Because the EGFR non-covalent inhibitor was prone to generate drug resistance during the treatment of cancer patients, the second-generation EGFR inhibitor afatinib was active at nanomolar levels in lung cancer cells through the covalent attachment to Cys797 of the mutant EGFR." (PMID 36431829, 2022). "However, its role in EGFR L858R/T790M mutant lung cancer cells has not yet been examined." (PMID 34830169, 2021). "The PD-1/PD-L1 axis may not be the main immune escape route in EGFR-mutant lung cancer." (PMID 34631565, 2021). "Other genetic tests that can be performed and are not part of the routine molecular diagnostics of lung cancer include the MET gene amplification test, especially in patients with progression during EGFR TKI therapy in the absence of the Thr790Met resistance mutation in exon 20 of the EGFR gene." (PMID 34945842, 2021). "The particular molecular features of early EGFR+ lung cancers and their potential impact on TKI efficacy now acquire direct clinical relevance due to the recent promising results of the ADAURA study, which might lead to routine adjuvant administration of osimertinib in the near future." (PMID 33898315, 2021). "Therefore, it may be concluded that RESV normalizes tumor angiogenesis in KRAS-mutant lung cancer but not in EGFR-mutant ones." (PMID 33652978, 2021). "In our analysis, based on the expression of BCL3 and EGFR in response to L4.5 sub-lineage when compared to L3-CAS1 sub-lineage, we hypothesize that infection by the L4.5 sub-lineage strain may be potent to deteriorate lung carcinoma by promoting tumor growth and angiogenesis." (PMID 33765916, 2021). "Thus, the dual inhibition of EGFR and MET might be a means to overcome lung cancer resistance." (PMID 32070026, 2020). "Although EGFR-TKI alone for brain metastasis in EGFR-mutant lung cancer showed outcomes comparable to those obtained with upfront RT followed by EGFR-TKI, a proportion of patients who could not receive RT following intracranial progression had the worst survival in this study." (PMID 32298306, 2020). "In addition, we have investigated the correlation between EZH2 expression and EGFR expression, KRAS expression, BRAF expression, and smoking in TCGA database to further explore the mechanism behind the influence of high EZH2 expression on lung cancer prognosis." (PMID 33299862, 2020).
lung cancer (continued). "The present study revealed that BBI608 could eradicate EGFR-positive lung cancers and demonstrated that STAT3 enhanced the expression of HER3 through miR-145-5p repression by G9a, indicating that STAT3 is a reliable therapeutic target against EGFR-TKI-resistant lung cancers." (PMID 31619200, 2019). "However, EGFR mutant lung cancers exhibit myeloid cell recruitment, but no CD8+ immune response was observed, suggesting that EGFR mutations may not be able to generate a sufficient antigen-driven immune response." (PMID 32039025, 2019). "Consequently, it was inferred that membrane trafficking of EGFR may be significantly perturbed in gefitinib-resistant cells, and that the trafficking machinery of SNX1 may play a suppressive function in regulating EGFR endocytosis in human lung cancer cells." (PMID 35582586, 2019). "Moreover, mutational activation of RTKs or downstream signaling proteins (e.g. EGFR/ERBB1, ALK, ROS1, NTRK, BRAF) serve as predictive biomarkers for the clinical deployment of FDA-approved inhibitors of these oncoprotein kinases for the treatment of genetically-defined subsets of lung cancer." (PMID 31452510, 2019). "However, EGFR TKI seems not to respond as well as lung cancer." (PMID 31579626, 2019). "For example, the epidermal growth factor receptor (EGFR) is frequently overexpressed in cancer cells and may be used to selectively target nanosystems (or drugs) via the therapeutic monoclonal antibody cetuximab (the FDA-approved drug for the treatment of colorectal and lung cancer)." (PMID 31694227, 2019). "Resistance may also be non-genetic and either related to cell state plasticity or to a specific molecular resistance pathway, such as aurora kinase activation in anti-EGFR-treated lung cancer, but further understanding of these non-heritable resistance mechanisms is needed." (PMID 30925887, 2019). "However, some studies have concluded that the in vitro EGFR sensitivity in neck squamous cell carcinoma and lung cancer is modulated by co-cultured fibroblast, indicating that the role of fibroblast in cancer drug resistance via EGFR mechanism should not be neglected." (PMID 30680600, 2019). "The RAS-PI3K interaction is thus an important signaling node and potential therapeutic target in EGFR-mutant lung cancer, even though RAS oncogenes are not themselves mutated in this setting, suggesting different strategies for tackling tyrosine kinase inhibitor resistance in lung cancer." (PMID 30590030, 2018). "However, whether miR‐1‐3p and miR‐206 can overcome HGF‐induced gefitinib resistance in EGFR mutant lung cancer is not clear." (PMID 29664235, 2018). "Hence EAI045 may not be an optimal agent to treat all EGFR C797S-related drug-resistant lung cancers, and new agents to inhibit EGFR L858R/T790M/C797S and Del-19/T790M/C797S, ideally without the help of a second agent such as Cetuximab, are needed." (PMID 29568384, 2018). "Although the development of brain metastases in general predicts a poor outcome in lung cancer, it is not known whether EGFR mutation-positive patients with brain metastases have a better prognosis as compared to EGFR mutation-negative patients, especially those in stages I to III lung cancer." (PMID 29447182, 2018). "Non-small cell lung cancer (NSCLC) represents approximately 85% of lung cancer cases, with most patients in Western populations having wild-type or unknown status for epidermal growth factor receptor (EGFR) and do not present anaplastic lymphoma kinase gene rearrangement." (PMID 29082855, 2017). "Having proved that EGFR increases SCD1 protein stability through Y55 phosphorylation, which is accompanied by up-regulation of SCD1 enzyme activity, we next explored whether high-level SCD1 expression and activity are indeed important for EGFR to promote lung cancer growth." (PMID 28724430, 2017).
lung cancer (continued). "Although EGFR status of the patient Satgé D reported could not be evaluated due to scarcity of histological material in biopsies, we speculate the patient's lung cancer was EGFR-wild type because of the European origin and not respond to the first-generation EGFR-TKI." (PMID 28903458, 2017). "However, our findings do not reflect the biology of those with EGFR mutant lung cancer and acquired EGFR kinase resistance, where these biomarkers may play a more important role." (PMID 29050231, 2017). "Whether TBK1 plays a role in EGFR mutant lung cancer is currently not known." (PMID 27613601, 2016). "As we demonstrated that there is a positive correlation between EGFR expression and PD-L1 expression status, the overexpression of EGFR may be a determinant of treatment response to immunotherapy targeting PD1/PD-L1 axis in the lung cancers that arise in these smoking population." (PMID 27467256, 2016). "However, PD 0332991 has not been tested in EGFR-TKI-resistant lung cancers." (PMID 27825114, 2016). "While several reports have found a higher incidence of brain metastases in patients with EGFR mutant lung cancers, it has never been shown whether this is due to a biologic propensity or simply a result of the longer survival of these patients due to EGFR targeted therapy." (PMID 26730601, 2016). "Consequently, treatments based on EGFR inhibition may not be sufficient for the effective treatment of lung-cancer patients with mutant EGFRs and it is necessary to inhibit IL-6/gp130/JAK pathway and further repress STAT3 activity in NSCLC treatment strategy." (PMID 26166037, 2015). "However, after the treatment of EGFR-TKI, the interactions of ERβ isoforms will induce the EGFR-TKI resistance by activating non-genomic signaling pathway (such as ERK1/2 and AKT) especially in EGFR mutant lung cancer cells with co-expression of ERβ1 and other ERβ isoforms (ERβ2 or ERβ5)." (PMID 26096604, 2015). "Therefore, TKI-sensitive lung cancer cell lines (PC9, exon 19 deletion; H3255, L858R EGFR mutant) and TKI-resistant lung cancer cell lines (PC9/gef, exon 19 deletion, acquired resistance; H1975, L858R/T790M EGFR mutant) were used to evaluate the anticancer effectiveness of digoxin." (PMID 25955608, 2015). "However, the therapeutic relevance of EGFR endocytosis in lung cancer has not been investigated." (PMID 24658031, 2014). "HGF could induce resistance to EGFR-TKIs via Met/PI3K/AKT activation, indicating that to overcome resistance to EGFR-TKIs induced by HGF-triggered activation of Met/PI3K/AKT pathway in mutant lung cancer, it was necessary to double blockade EGFR and HGF-Met signaling pathways." (PMID 23533466, 2013). "Given the importance of EGFR signaling as a therapeutic target in lung cancer, further examination of the effect of EGF, heregulin, and amphiregulin on GPER expression and function in lung cancer may provide new insights into resistance to EGFR inhibitors and or how estrogens stimulate lung cancer." (PMID 23273253, 2012). "Although the same may be true for other cancers including breast cancer, data regarding the presence or absence of EGFR abnormalities in tumors other than lung cancer and the response of such tumors to anti EGFR therapy are still limited and rather conflicting." (PMID 21702909, 2011). "Interestingly, in both erlotinib and gefitinib NSCLC randomized trials approximately 30% of the patients died within 4 months of treatment time, which strongly suggest that there is a subset of lung cancer patients who receive no clinical benefit from EGFR-TKI therapy." (PMID 16911776, 2006). "The SEER database does not present molecular markers, including EGFR, ALK, and ROS1, which are critical in guiding the prognosis and therapy for lung cancer BM." (PMID 40098698, 2025). "Efficacy in a checkpoint inhibitor resistant setting was also seen in patient 20202 with EGFR and ALK negative non–small cell lung cancer (NSCLC) refractory to nivolumab therapy." (PMID 38546220, 2024).
lung cancer (continued). "A panel of lung cancer cells has been tested, and the data showed that BEZ235 reduces cell proliferation in vitro regardless of their EGFR status and suppresses tumor growth in a mouse xenograft model using H1975 cells." (PMID 38203787, 2024). "Using normal human, prostate/lung cancer (DU145/A375) and other cell lines, we showed that 2D5, but not Ctrl, inhibited EGFR-mediated signaling and cell proliferation." (PMID 38745775, 2024). "Lapatinib, a dual inhibitor of EGFR and HER2, has not yet been used in the treatment of lung carcinoma in dogs." (PMID 39902337, 2024). "RepID is a crucial player for cell proliferation in driver-negative tumors, including melanoma, breast, and lung cancers which lose HER2, EGFR, ALK, or BRAF expression." (PMID 37461562, 2023). "KRAS is activated as a consequence of the phosphorylation of EGFR, however targeting ERBB RTK signaling using erlotinib and gefitinib showed no impact on disease progression in KRAS-mutant lung cancers." (PMID 36899885, 2023). "The EGFR pathway is a widely recognized oncogenic pathway for non-small cell lung cancer (NSCLC), which represents approximately 75% of lung cancers." (PMID 37601068, 2023). "Compared with control human lung cancer cell lines PC‐9 and A925L, KM12SM and HCC78 cells expressed lower levels of EGFR and no detectable levels of FGFR1." (PMID 36416133, 2023). "As expected, KAN0441571C induced dephosphorylation of ROR1 in a dose-dependent manner, as well as EGFR, SRC, PI3K110δ/AKT/mTOR (non-canonical Wnt pathway), and CREB in the NCI-H23 lung cancer cell line." (PMID 37111634, 2023). "Asian patients with adenocarcinoma have higher prevalence of unique biologic features such as a higher incidence of oncogene-driven NSCLC (mainly EGFR-mutant and ALK-rearranged tumors), and the majority of Asian women with lung cancer are never-smokers." (PMID 36650586, 2023). "Nuclear localization of AhR has been reported to be more common in lung cancer from women, non-smokers, adenocarcinoma and NSCLC patients with the EGFR exon 19 (E746–750A) deletion." (PMID 37696458, 2023). "IL-6 was decreased in both of the erlotinib-sensitive EGFR-mutant lung cancer cell lines (HCC4006 and HCC827) and was not changed in the erlotinib-resistant EGFR-mutant lung cancer line (H1975) after erlotinib treatment." (PMID 36612121, 2022). "Although immune checkpoint inhibitors (ICIs) have revolutionized treatment strategies of lung cancer, the overall response rate of ICI monotherapies is still limited and no more than 20% in NSCLC patients with EGFR/ALK wild-type." (PMID 35677561, 2022). "Yang A analyzed a total of 1,001 lung cancer retrospectively, and showed that the HR of VTE occurrence is 2.808 (95% CI: 1.439–5.479, p = 0.002) in patients with EGFR-TKI treatment relative to patients without the treatment." (PMID 35321110, 2022). "Although a circRNA from epidermal growth factor receptor (EGFR) has been reported in mouse ovaries during postnatal development with a marked expression profile, the implication of this circRNA in lung cancer has not been studied yet." (PMID 39697533, 2021). "Although previous studies have reported that ESB triggered apoptosis and cell cycle arrest and inhibited the migration and invasion of human lung cancer cells, they did not focus on the activity of ESB in EGFR TKI-resistant cell lines." (PMID 34068421, 2021). "Unlike the routine detection of HER2, EGFR, BRAF, KRAS and other genes in breast cancer, lung cancer, colorectal cancer and other tumors, HCC has not yet an apparent gene-phenotype related to its prognosis and treatment due to its heterogeneity." (PMID 35071004, 2021). "In lung cancer, METTL3 promoted translation of oncogenic mRNA, epidermal growth factor receptor (EGFR), independent of its catalytic activity." (PMID 32900991, 2020).
lung cancer (continued). "Consequently, we evaluated if the assessment of the EGFR status in NSLC biopsies using an EGFR-specific PCR assay still has a place in the daily practice of an academic hospital center, and how this single gene testing approach could be integrated into lung cancer patient care." (PMID 32294880, 2020). "Despite the anti-angiogenesis effects of EGFR-TKIs, no studies on the effects of the EGFR-TKIs Gefitinib, Afatinib, and AZD9291 on lymphangiogenesis in lung cancer have been reported." (PMID 31892990, 2020). "This strategy has been successful in vitro and in vivo in targeting the Ras/MAPK, EGFR, and IGF-1R kinases in ALK fusion-positive lung cancer, but is not yet applied in the clinic." (PMID 30813562, 2019). "Many laboratories find this easier as lung cancer cases can be batched with other (e.g. colorectal cancer) cases undergoing KRAS testing, rather than waiting for sufficient EGFR or ALK testing samples." (PMID 30470932, 2019). "However, in lung cancer, acquired anti-EGFR TKI resistance could not be overcome by cetuximab." (PMID 31546690, 2019). "Expression of apoptosis related marker, cleaved-PARP, was measured following treatment with EGFR TKIs, Gefitinib (first-generation EGFR TKIs), with or without CHIR-99021 in MCTS with NCI-H460 cells (EGFR WT lung cancer cell lines) and HUVEC cells." (PMID 30709379, 2019). "This also echoes the clinical trial results that MetMab, in combination with EGFR inhibitor erlotinib, failed to improve efficacy in a phase III lung cancer trial." (PMID 30208970, 2018). "The KRAS gene is mutated in approximately 20% of NSCLC cases, and the EGFR gene is defective in approximately 10% of NSCLC patients and in nearly 50% of non-smoker lung cancer cases." (PMID 29912931, 2018). "In summary, our studies demonstrate that PHLDA2 is strongly regulated by EGFR/ErbB2 signaling and inhibits cell proliferation via repressing AKT activation in lung cancers in a negative feedback loop." (PMID 29861842, 2018). "However, other factors (mainly related to driver gene alterations in lung cancer, such as EGFR and ALK) were not reported, as well as the information about treatment with targeted therapy for oncogene-addicted tumours (which may confound the results in the adenocarcinoma subset)." (PMID 28846697, 2017). "Despite the successful development of EGFR- or EML4-ALK-targeted TKIs, treatment options remain limited for patients with advanced lung cancer lacking an identifiable oncogenic driver alteration." (PMID 28806950, 2017). "NEU3 and EGFR were not overexpressed in any of the analyzed lung cancer cell lines; NEU3 mRNA levels were never significantly higher than 1, while EGFR mRNA levels were found downregulated in all cases, with a highest value of 0.5." (PMID 29088281, 2017). "Although EGFR and ALK inhibitors are established in EGFR mutant and ALK rearranged lung cancer, there are currently no molecularly targeted agents licensed for use in the remainder of adenocarcinomas (NSCLC-adeno-EGFRWT/ALKnon-rearranged)." (PMID 27441499, 2016). "The present study reveals that TOPK is highly expressed in lung cancer but not in paraneoplastic tissues, and that excessive TOPK confers resistance of cancer cells to EGFR-TKIs." (PMID 26745678, 2016). "IGF-1 alone does not promote lung cancer cell proliferation (data not shown), however IGF-1 induced PC-9 and H460 cells showed decreased sensitivity to EGFR-TKIs compared to parental cells." (PMID 26554308, 2015). "In this study, we have demonstrated that in human lung cancer cells, gefitinib treatment induces, rather than suppresses STAT3 activation as extrapolated from traditional EGFR signaling orthodox." (PMID 24280348, 2013). "The results of this study demonstrated that downregulation of activated EGFR, in the NCI-H1975 lung cancer cell line, did not, in fact, correlate with upregulation of RBM5, suggesting that RBM5 functions upstream of EGFR." (PMID 22537942, 2012).